DRG1 (developmentally regulated GTP binding protein 1)
Diseases named in the same sentence as DRG1 in open-access papers (continued):
Sharing a sentence is not in itself a finding about the gene and the disease.
tumor (14 papers, 2003 to 2025). "The present study found that DRG1 was abnormally up-regulated in OS tissue compared with paracancerous tissues, and that up-regulated DRG1 was associated with big tumor size and advanced clinical stages of OS." (PMID 32266933, 2020). "High expression level of DRG1 was associated with big tumor size (P<0.05) and advanced clinical stages of OS (P<0.05)." (PMID 32266933, 2020). "In summary, high expression level of DRG1 was associated with big tumor size and advanced clinical stages of OS." (PMID 32266933, 2020). "DRG1 knockdown causes growth inhibition of tumor cells by significantly increasing the proportion of cells in M phase." (PMID 27626498, 2016). "High expression of DRG1 was associated with large tumor size and advanced clinical stages in OS." (PMID 32266933, 2020). "We showed that loss of DRG1 induced mitosis arrest and growth inhibition in tumor cells." (PMID 27626498, 2016). "MTTL3 has been associated with the overexpression of the DRG1 (developmentally regulated GTP binding protein 1) gene, which promotes tumor growth and metastasis in OS." (PMID 40868849, 2025). "Knockdown of DRG1 causes growth inhibition in M phase of HeLa, A549, and H1299 tumor cells, and vice versa, the overexpression of DRG1 leads to chromosomal missagregation." (PMID 35790840, 2022). "In order to test the biological function of sponge DRG1 and compare it to human DRG1, we analysed the function of exogenous sponge and human DRG1 in human tumor cells." (PMID 35790840, 2022). "Using primary antibody immunoprecipitation we confirmed the interaction of DRG1 with its co-expressing proteins in tumor cell lines." (PMID 27626498, 2016). "Consistent with the results of DRG1 mRNA expression, DRG1 protein level was also highly up-regulated in adenocarcinoma tumor tissues compared with the adjacent tissues in 5 out of 6 patients." (PMID 27626498, 2016). "Consistent with our findings, DRG-1 knockdown decreased non-small cell lung cancer (NSCLC) tumor growth in vivo." (PMID 25993655, 2015). "In contrast to these studies, we found that GJB2 is underexpressed in tumours and DRG1 is overexpressed." (PMID 14612907, 2003). "Further, different tumor cell lines exhibit high levels of DRG1 mRNA2." (PMID 35790840, 2022). "However, the possible relationship between DRG1 and tumor initiation and progression remains unexplained." (PMID 35790840, 2022). "However, the molecular basis of DRG1 in cell proliferation regulation and the relationship between DRG1 and tumor progression remain poorly understood." (PMID 27626498, 2016). "Levels of DRG1 transcript were analyzed in connection with tumour grade." (PMID 24213460, 2012). "The positive or negative association of Drg-1 with cell differentiation depends on tumor types." (PMID 23013480, 2012). "Furthermore, DRG1 has been shown to be overexpressed in other tumours." (PMID 14612907, 2003). "ELAVL1 promotes the expression of certain tumor-related genes, such as ZMYM1 and DRG1, in an m6A-dependent manner, thereby exerting pro-carcinogenic effects." (PMID 37744335, 2023). "When co-transfected in different tumor cell lines, co-localization of DRG1 and DFRP1 was previously shown in the cytosol of human tumor cells HeLa S3, mouse 3T3 cells and Drosophila melanogaster cells." (PMID 35790840, 2022). "In the present study, we demonstrated that ZC3H15, which interacts with DRG1, is highly expressed in HCC and regulates tumor cell proliferation in vitro and in vivo." (PMID 27191988, 2016).
cancer (8 papers, 2012 to 2023). A tumor composed of atypical neoplastic, often pleomorphic cells that invade other tissues. "DRG1 is an evolutionary conserved GTPase that has been implicated in various tumors, but its role in cancer is not yet fully understood." (PMID 36827160, 2023). "A growing number of studies have shown that abnormal expression of DRG1 is associated with occurrence and development of cancer." (PMID 32266933, 2020). "Developmentally regulated GTP-binding protein (DRG) 1 plays an important role in embryonic development; aberrantly expressed DRG1 has been associated with pathological processes in cancer." (PMID 32266933, 2020). "A large number of studies have identified DRG1 as a gene that is down regulated in cancer and associated with metastasis suppression, however there are some studies that suggest differing roles." (PMID 24213460, 2012). "Therefore, it has been suggested that the loss of DRG1 may contribute to genomic instability in cancer cells." (PMID 24213460, 2012). "Previous studies reported that METTL3 and 14 act as oncogenes in several types of cancer by regulating DRG1 and MYC, respectively." (PMID 35794212, 2022). "For example, DRG1 can interact with other cancer-related proteins, such as c-myc, ras, and SCL/TAL114,15." (PMID 35790840, 2022). "Consistent with the DRG1/DFRP1 complex being required for cancer cell proliferation there is emerging evidence supporting an oncogenic role in cancer." (PMID 34664086, 2021). "In conclusion, DRG1 exerted cancer-promoting effects on OS, and up-regulated DRG1 in OS was induced by METTL3 and ELAVL1 in an m6A-dependent manner." (PMID 32266933, 2020). "The molecular mechanisms of DRG-1 in cancer development and progression require further investigation." (PMID 25993655, 2015). "While there is some controversy regarding the relationship of DRG1 expression to the suppression of metastasis in certain cancers, the majority of studies have demonstrated that higher levels lead to a less aggressive phenotype." (PMID 24213460, 2012). "Beside through its role in mitosis, DRG1 could be involved in cancer biology due to its additional function(s)." (PMID 35790840, 2022). "Aberrantly expressed DRG1 has been observed in other types of cancers, but up-regulated DRG1 is not always associated with the worst types of cancer." (PMID 32266933, 2020). "Since abnormal cellular proliferation is a characteristic of cancer cells, ectopic expression of DRG1 may contribute to the dysregulation of this normal control mechanism and induce tumorigenesis." (PMID 27626498, 2016). "Several studies have indicated that DRG-1 may influence cancer growth and progression by modulating angiogenesis." (PMID 25993655, 2015). "DRG1 has been shown to be upregulated by iron chelators in a variety of cancer cell lines." (PMID 24213460, 2012). "Considering the role of DRG1 in metastasis suppression, it was proposed that its expression could be used as a prognostic marker in cancer patients." (PMID 24213460, 2012). "DRG1 has been shown to play an important role in the context of human cancer progression." (PMID 24213460, 2012). "Therefore, DRG1 apparently plays different roles in diverse type of cancers." (PMID 32266933, 2020). "Overall, level of DRG1 expression could help to predict the sensitivity of cancer cells to taxol." (PMID 27626498, 2016). "Our study, as well as other studies, confirmed the localization of DRG1 in the cytosol of various cell lines (MCF-7 and HeLa human cancer cell lines, mouse 3T3 cells, and Drosophila melanogaster cells)." (PMID 36827160, 2023). "The expression of the human DRG1 protein requires the DFRP1 protein for its stabilization and localization in the cytosol of human cancer cells MCF-7 and HeLa." (PMID 36827160, 2023). "Considering all the available data, the exact biological function of DRG1/DFRP1 and its role in the most common diseases such as cancer, are not yet fully understood." (PMID 35790840, 2022).
cancer (continued). "Several papers have suggested that DRG1, DRG2 and DFRP1 are required for the growth and proliferation of various cancer cell lines." (PMID 34664086, 2021). "The fact that sponges do not have cancer emphasizes the importance of DRG1 in fundamental cellular pathway(s)." (PMID 35790840, 2022). "Due to high evolutionary conservation of the DRG1/DFRP1 complex, its link to basic cellular processes and role in cancer, research on DRG1 could significantly improve the understanding of these subjects." (PMID 35790840, 2022). "Besides conserved binding of DRG1 and DFRP1, these findings also confirm the identical localization of EsuDRG1 and HsaDRG1, which may indicate their similar role(s) in human cancer cells." (PMID 35790840, 2022). "We demonstrate the conservation of sponge and human DRG1 biological features, including intracellular localization and DRG1:DFRP1 binding, function of DRG1 in α-tubulin dynamics, and its role in cancer biology demonstrated by increased proliferation, migration and colonization in human cancer cells." (PMID 35790840, 2022).
infection (1 paper, 2022). The state of being infected such as from the introduction of a foreign agent such as serum, vaccine, antigenic substance or organism. "Thus, further development could be focused on the modification benzyl group to increase its affinity for Drg1 to treat fungi infection." (PMID 36351914, 2022).
DRG1 also shares sentences with these, for which no sentence is quoted: adenocarcinoma (1 paper); bladder carcinoma (1); cervical adenocarcinoma (1); esophageal squamous cell carcinoma (1); head and neck squamous cell carcinoma (1); Insulin resistance (1); meningioma (1); neuroblastoma (1).